PRPF19 (pre-mRNA processing factor 19)
Diseases named in the same sentence as PRPF19 in open-access papers (continued):
Sharing a sentence is not in itself a finding about the gene and the disease.
glioblastoma (1 paper, 2020). The most malignant astrocytic tumor (WHO grade IV). "Functional evidence for chemosensitivity, however, was validated for PRPF19 by gene silencing in glioblastoma cells." (PMID 32991787, 2020). "Depletion of PRPF19 expression resulted in the anticipated sensitization to temozolomide in glioblastoma cell lines and primary cell cultures, and may therefore, be investigated further as a predictive marker in MGMT promoter unmethylated glioblastoma." (PMID 32991787, 2020). "PRPF19 was previously reported to be involved in DDR24 and has a potential role in oncogenesis, but little is known about its function in glioblastoma." (PMID 32991787, 2020).
liver cancer (1 paper, 2022). An epithelial or non-epithelial malignant neoplasm that arises from the liver. "Here, intending to assess the clinical value of PRPF19 in liver cancer, we performed a multi-dimensional analysis of integrated tumor immunity, somatic mutation, and functional networks to capture multiple aspects of information of PRPF19 in LIHC." (PMID 35252202, 2022). "To further study the mechanism of PRPF19-mediated progression in liver cancer, we carried out an enrichment analysis of differential genes elicited by PRPF19 from the expression profiling of LIHC-TCGA." (PMID 35252202, 2022). "To annotate the expression of PRPF19 in normal liver tissues and liver cancer, we integrated single-cell sequencing (scRNA-seq) data from the Human Protein Atlas (HPA)." (PMID 35252202, 2022). "We then analyzed the levels of methylation of the PRPF19 promoter using the UALCAN dataset in liver cancer." (PMID 35252202, 2022). "Together, these results suggested that high expression of PRPF19 is a poor prognostic factor in liver cancer." (PMID 35252202, 2022). "Using various databases and tools (UALCAN, TIMER, TISMO, and PathCards), we presented the potential mechanisms of PFPF19 upregulation, PRPF19-related pathways, and its biological functions in liver cancer." (PMID 35252202, 2022). "We thought that the dysregulation of genes tightly related to PRPF19 may play an important role in contributing to liver cancer progression." (PMID 35252202, 2022). "Next, we further explored the relationship between MDSCs and PRPF19 in liver cancer." (PMID 35252202, 2022). "Additionally, the elevated transcript level of PRPF19 correlated with decreased response to antiPD1 treatment according to the syngeneic liver cancer mouse model data." (PMID 35252202, 2022). "Moreover, in different subgroups, in both the advanced stage and the vascular invasion group, the survival curves of OS diverged further with the increasing length of follow-up, which suggests that high PRPF19 expression is a marker of poor prognosis for patients with liver cancer." (PMID 35252202, 2022). "Therefore, the role of the oncogene of PRPF19 in liver cancer may account for its ability to promote functions such as angiogenesis, proliferation, and immune escape." (PMID 35252202, 2022). "Given the PRPF19 aberrant expression may abrogate the antitumor mechanism in humans, we did a comprehensive analysis of the clinical phenotypes and biological information relevant to this molecule in liver cancer." (PMID 35252202, 2022).
mandibulofacial dysostosis (1 paper, 2025). A hereditary disorder occurring in two forms: the complete form (Franceschetti's syndrome) is characterized by antimongoloid slant of the palpebral fissures, coloboma of the lower lid, micrognathia and hypoplasia of the zygomatic arches, and microtia. "Similarly, EFTUD2 mutations result in mandibulofacial dysostosis with microcephaly, and mutations in PPIL1, PRP17, and PRPF19 are linked to neurodegenerative pontocerebellar hypoplasia." (PMID 40608414, 2025).
metastasis (1 paper, 2023). The spread or migration of cancer cells from one part of the body (where they first appeared) to another. "Clinically, the expression of PRPF19 was positively correlated with liver metastasis, and predicted an unfavorable prognosis for patients with CRC." (PMID 37031206, 2023).
ovarian carcinoma (1 paper, 2017). A malignant neoplasm originating from the surface ovarian epithelium. "To date, PRPF19 has not been studied in ovarian cancer; however, these previous studies imply that the gain of PRPF19 is a critical event during the progression of cancer, making it a promising target for malignancies with aberrant PRPF19 expression." (PMID 28122348, 2017).
pancreatic cancer (1 paper, 2023). "For example, LINC00673 enhances the interaction of PTPN11 with the ubiquitin ligase PRPF19 and promotes PTPN11 degradation through ubiquitination in pancreatic cancer." (PMID 36846713, 2023).
pancreatic ductal adenocarcinoma (1 paper, 2021). An infiltrating adenocarcinoma that arises from the epithelial cells of the pancreas. "For example, through binding with PRPF19 and PTPN11, LINC00673 strengthens the PRPF19–PTPN11 interaction, contributing to enhance PRPF19‐mediated ubiquitination and degradation of PTPN11 in pancreatic ductal adenocarcinoma." (PMID 34337858, 2021).
viral infection (1 paper, 2022). "We further demonstrated that pre-mRNA-processing factor 19 (PRP19) is a positive regulator for replication of influenza A virus, whereas 14-3-3ε serves as a negative regulator during viral infection." (PMID 35889979, 2022).
tumor (23 papers, 2009 to 2025). "To confirm this issue, we validated the expression levels of PRPF19 in patients’ tumor tissues and CRC cell lines." (PMID 37031206, 2023). "We noticed that upregulation of PRPF19 was detected in liver metastasis tumor tissues of CRC in a large-scale proteogenomics study, however, there was no report concerning the role of PRPF19 in CRC." (PMID 37031206, 2023). "Pre-mRNA processing factor 19 (PRPF19) is an E3 ligase that plays a crucial role in repairing tumor-damaged cells and promoting cell survival." (PMID 38022515, 2023). "PRPF19 is a predictive factor for worse clinical outcomes in HBV-related HCC and is associated with tumor immune evasion and progression." (PMID 36275676, 2022). "As PRPF19 was correlated with pretreatment tumor staging and tumor biology, we then performed gene set enrichment analysis (GSEA) using the MSigDB hallmark gene sets, reactome, and C6 gene sets." (PMID 35252202, 2022). "A significant reduction of mean methylation levels for PRPF19 was found in the tumor group compared with normal tissues." (PMID 35252202, 2022). "As expected, tumor purity and the infiltration level of the MDSCs were accompanied by elevated PRPF19." (PMID 35252202, 2022). "According to the tumor-immunological analysis, we found that PRPF19 is positively correlated with infiltrating myeloid-derived suppressor cells (MDSCs)." (PMID 35252202, 2022). "For example, lncRNA LINC00673 inhibits tumor progression via reinforcing the interaction of PTPN11 with PRPF19 and facilitated STAT1-dependent antitumor response." (PMID 34322379, 2021). "Among them, aminoacylase-1, pre-mRNA-processing factor 19, T-complex protein 1 subunit α and T-complex protein 1 subunit β (TCP1β) are reported for the first time to be differentially expressed between tumor and normal colon mucosa." (PMID 21973086, 2011). "Additionally, the expression of PRPF19 significantly increased in liver metastasis tumor tissues compared with that in paired primary tumor tissues." (PMID 37031206, 2023). "Moreover, the expression of PRPF19 was also positively correlated with tumor size (p = 0.004), tumor invasion (p = 0.024), and the presence of lymph nodes (p = 0.022) and liver metastasis (p = 0.011)." (PMID 37031206, 2023). "We hypothesized that elevated PRPF19 expression may influence antitumor immunity by recruiting immunosuppressive cell population in the tumor microenvironment." (PMID 35252202, 2022). "Furthermore, our results reveal that the main infiltrating immune cells with tumor-killing abilities were significantly reduced in the tumors with high expression of PRPF19." (PMID 35252202, 2022). "Pre-mRNA processing factor 19 (Prp19) was previously reported to be involved in tumor progression." (PMID 33224878, 2020). "Moreover, after addition of tumor purity into the multivariate model, only PRPF19 (P = .005‐.04, c‐index = 0.71‐0.73) and TP73 (P = .02‐.04, c‐index = 0.71‐0.72) methylation were significantly associated with better OS and PFS." (PMID 32991787, 2020). "Similarly, clonogenicity of tumor cells treated with temozolomide was reduced particularly in PRPF19 and TERT knockdown cells." (PMID 32991787, 2020). "While HUWE1, UBR5, PRPF19, ARIH2 and OBI1 are mainly related to tumor suppression, DNA damage response and DNA replication, TRIM21 is involved in regulating host innate immunity and viral immune evasion." (PMID 38932241, 2024). "It is worth mentioning that the expression of PRPF19 is increased in the liver metastasis tumor tissues of CRC in a large-scale proteogenomics study, which drew our attention to evaluate the biological behavior of PRPF19 in CRC." (PMID 37031206, 2023). "A previous study has revealed that PRPF19 is upregulated in liver metastasis tumor tissues of CRC in a large-scale proteogenomics study, implying that PRPF19 may be a regulator of tumor metastasis in CRC." (PMID 37031206, 2023).
tumor (continued). "Although previous studies have reported that PRPF19 participated in tumorigenesis in several tumor types, its role in cancer is still not well characterized to date." (PMID 37031206, 2023). "LINC00673 is also clarified to suppress tumor progression by enhancing the binding of pre-mRNA processing factor 19 (PRPF19) to protein tyrosine phosphatase non-receptor type 11 (PTPN11), subsequently promoting PRPF19-mediated ubiquitination and degradation of PTPN11." (PMID 38174069, 2023).
cancer (21 papers, 2011 to 2024). A tumor composed of atypical neoplastic, often pleomorphic cells that invade other tissues. "As Tert is an important aging-related gene and Prpf19 is involved in DNA repair, it would be interesting to test whether these differences are linked to the extreme longevity and/or cancer resistance of the NMR." (PMID 35039495, 2022). "PRPF19, apart from its involvement in cellular biological mechanisms, exerts a significant regulatory function in many pathological conditions, such as cancers, by virtue of its multipotency." (PMID 38022515, 2023). "In this study, we first evaluated the expression level of PRPF19 in various types of cancer, and the data revealed that the expression of PRPF19 was upregulated in pan-cancers." (PMID 37031206, 2023). "Consistent with other cancers, PSMB5, TPR, and PRPF19 were independent prognostic risk factors in BCa, while PSMD14 seemed to be a protective factor, which was different from other types of cancers." (PMID 35898492, 2022). "Despite this, it was surprising that higher expression of several genes from clusters 1 and 2 (e.g., PRPF19 and ATRIP) were strongly associated with better overall survival in some cancer groups." (PMID 34853396, 2021). "Since that MYL9 contributes to the stiffer matrix and leads to Src activation, and Src is a well-known upstream driver of YAP in cancer metastasis, we supposed that the PRPF19/MYL9 may regulate the Src/YAP pathway in CRC." (PMID 37031206, 2023). "Therefore, further investigation of the relationship between PRPF19 and MDM4 in cancer cells would contribute to improvements in cancer diagnosis and therapy." (PMID 34144037, 2021).
infection (3 papers, 2020 to 2025). The state of being infected such as from the introduction of a foreign agent such as serum, vaccine, antigenic substance or organism. "Among the top 5 hub genes, pre-mRNA processing factor 19 (PRPF19) with high connectivity (kME) and correlation with infection in Turquoise (the largest module in this study) was selected as a possible genetic marker." (PMID 32131541, 2020).
neurodevelopmental disorder (2 papers, 2024 to 2025). A behavioral and cognitive disorder with onset during the developmental period that involves impaired or aberrant development of intellectual, motor, or social functions. "Importantly, PRPF19 and other spliceosome components have been associated with neurodevelopmental disorders." (PMID 40650163, 2025). "Spliceosome defects involving U2AF2, PRPF19, and RBFOX1 variants contribute to neurodevelopmental disorders by disrupting neuritogenesis and brain development." (PMID 37962958, 2024).
neurological diseases (1 paper, 2023). "However, the neuronal function of human PRPF19 has rarely been investigated, and its involvement in human neurological diseases remains unexplored." (PMID 36980356, 2023).
PRPF19 also shares sentences with these, for which no sentence is quoted: glioma (2 papers); autism (1); Azoospermia (1); benign prostatic hyperplasia (1); breast tumors (1); cervical cancer (1); developmental delay (1); endometrial cancer (1); germ cell tumor (1); lung carcinoma (1); melanoma (1); mesothelioma (1); microcephaly (1); Obesity (1); prostate adenocarcinoma (1); rectal cancer (1); T-cell ALL (1).